PTH1R (parathyroid hormone 1 receptor)
Diseases named in the same sentence as PTH1R in open-access papers (continued):
Sharing a sentence is not in itself a finding about the gene and the disease.
Eiken syndrome (12 papers, 2015 to 2025). Eiken syndrome is a rare familial skeletal dysplasia characterized by multiple epiphyseal dysplasia, with extremely retarded ossification. "The functional studies thus identified two distinct mechanisms by which Eiken syndrome PTH1R mutations destabilize interaction with βarrestin and hence lead to impaired desensitization of cAMP signaling." (PMID 40904804, 2025). "In contrast to R485X, the E35K and Y134S PTH1R mutations, also found in Eiken syndrome, alter residues in the receptor’s N-terminal ECD." (PMID 40904804, 2025). "PTH1R mutations cause skeletal dysplasias, including Jansen's metaphyseal chondrodysplasia, Eiken syndrome and Blomstrand chondrodysplasia." (PMID 41000054, 2025). "Altered Signaling and Desensitization Responses in PTH1R Mutants Associated with Eiken Syndrome have been described." (PMID 38331475, 2024). "A different homozygous PTH1R mutation was recently identified in a child from a consanguineous family who exhibited delayed ossification, consistent with Eiken syndrome, but also marked PTH-resistance (hypocalcemia with elevated PTH)." (PMID 37268817, 2023). "Here we present a cell-based functional characterization of three Eiken syndrome-associated PTH1R mutations: R485X, E35K, and Y134S." (PMID 37268817, 2023). "Eiken syndrome is a rare disease of delayed bone mineralization caused by homozygous PTH1R mutations." (PMID 37268817, 2023). "PTH1R mutations have been reported in conditions such as Blomstrand chondrodysplasia and Eiken syndrome, which may present with variable skeletal findings and end-organ PTH resistance." (PMID 41322012, 2025). "Patients with delayed ossification (Eiken syndrome) can exhibit features of both gain-of-function effects of the mutant PTH1R toward PTHrP in developing bone but also loss-of-function effects toward PTH in the kidney (PTH-resistance) or toward PTHrP in developing teeth (PFTE)." (PMID 40904804, 2025). "The R485X truncation, found in Eiken syndrome, results in the loss of most of the PTH1R C-tail, which is important for normal receptor desensitization and the translocation of the receptor from the plasma membrane to endosomes, as mediated by the binding of β-arrestin to the phosphorylated C-tail." (PMID 40904804, 2025). "It was nearly two decades later, in 2005, that Eiken syndrome was ascribed to PTH1R mutations." (PMID 40904804, 2025). "These include delayed ossification in Eiken syndrome, hypocalcemia in a pseudohypoparathyroidism-like disorder, and non-syndromic primary failure of tooth eruption; which is usually caused by heterozygous PTH1R mutations." (PMID 40904804, 2025). "Recessive mutations in PTH1R have been identified in patients with Eiken syndrome and BOCD, but the clinical manifestations were opposite and might have different molecular underpinnings." (PMID 37840415, 2023). "In any case, it is clear that the LOF effects of these three homozygous mutations of Eiken syndrome are milder than those conferred by the LOF PTH1R mutations, such as P132L, that, when homozygous, result in the neonatal lethal condition of Blomstrand chondrodysplasia." (PMID 37268817, 2023). "In fact, in the growth plates where local PTHrP levels are expected to be abundant, inefficient PTH1R desensitization is likely to enhance activation of the down-stream signaling pathway resulting in the delayed chondrocyte differentiation that underlies the mineralization defect in Eiken syndrome." (PMID 40904804, 2025). "It was previously suggested that the delayed ossification seen in Eiken syndrome patients with the PTH1R-R485X variant might arise from an impaired capacity of the mutant receptor to activate the Gαq/phospholipase C (PLC)/inositol triphosphate (IP3)/intracellular calcium (iCa2+) signaling." (PMID 37268817, 2023).
Eiken syndrome (continued). "In addition to PFE, PTH1R mutation is also associated with four more clinically overlapping human disorders per the type of mutation: Jansen’s metaphyseal chondrodysplasia, Eiken syndrome, which is a skeletal disorder, Blomstrand osteochondrodysplasia, and Ollier disease." (PMID 29544499, 2018). "Diseases associated with PTH1R include chondrodysplasia, blomstrand type (OMIM: 215,045), metaphyseal chondrodysplasia, Jansen type (OMIM: 156,400), Eiken syndrome (OMIM: 600,002) and primary failure of tooth eruption (OMIM: 125,350)." (PMID 40462134, 2025). "The other clinical manifestations of Eiken syndrome, however, such as the mild PTH resistance and PFTE, are more likely explained by a loss-of-function effect on PTH1R signaling responses in kidney and teeth, as mediated by PTH and PTHrP, respectively." (PMID 40904804, 2025). "The clinical phenotypes in the reported cases of Eiken syndrome are somewhat variable as some patients also exhibit features that are most easily attributed to LOF effects on the PTH1R." (PMID 37268817, 2023). "Mutations in PTH1R are associated with Jansen‐type metaphyseal chondrodysplasia (JMC), Blomstrand osteochondrodysplasia (BOCD), Eiken syndrome, enchondroma, and primary failure of tooth eruption (PFE)." (PMID 37840415, 2023). "Mutations in the PTH1R gene resulted in PFE, JCM, Eiken syndrome, BOCD, enchondroma, and pseudohypoparathyroidism." (PMID 37840415, 2023). "Mutations in the PTH1R gene are known to cause Jansen's metaphyseal chondrodysplasia (MIM #156400), chondrodysplasia Blomstrand type (MIM #215045), Eiken syndrome (MIM #600002), and failure of tooth eruption (MIM #125350)." (PMID 33536578, 2021).
Hypercalcemia (11 papers, 2016 to 2025). An abnormally increased calcium concentration in the blood. "Finally, the loss of sustained signaling by the PTH1R and CaSR have been associated with hypo- and hypercalcemia, respectively, further demonstrating the importance of such signaling in physiology." (PMID 39743506, 2025). "However, Jansen’s metaphyseal chondrodysplasia is caused by activation of mutations in PTH1R, leading to hypercalcemia, and bisphosphonates are used to treat this condition." (PMID 39598431, 2024). "Jansen chondrodysplasia (MIM #156400) originates from a mutation in PTH1R that results in permanent activation of the subsequent signaling pathways resulting in a dwarfism phenotype, micrognathia, disorganized metaphyseal areas of the bones, hypercalcemia and hypophosphatemia." (PMID 27898723, 2016). "Jansen's metaphyseal chondrodysplasia (JMC) is an ultra-rare autosomal dominant disease that is caused by heterozygous, activating PTH1R mutations resulting in PTH- and PTHrP-independent hypercalcemia and hypercalciuria, leading to nephrocalcinosis and impaired renal function later in life." (PMID 39950977, 2025). "Jansen metaphyseal chondrodysplasia (JMC) is an ultra-rare autosomal dominant disease that is caused by heterozygous, activating PTH1R mutations resulting in PTH- and PTHrP-independent hypercalcemia and hypercalciuria, leading to nephrocalcinosis and impaired renal function later in life." (PMID 39950977, 2025). "Consequently, allosteric modulators of PTH1R seem to be a potential drug in the treatment of PHPT-induced hypercalcemia and bone disease secondary to it, but it needs further research." (PMID 39519190, 2024). "Activating parathyroid hormone (PTH)/PTH‐related Peptide (PTHrP) receptor (PTH1R) mutations causes Jansen's metaphyseal chondrodysplasia (JMC), a rare disease characterized by growth plate abnormalities, short stature, and PTH‐independent hypercalcemia." (PMID 37808400, 2023).
hypoparathyroidism (9 papers, 2011 to 2025). Hypoparathyroidism is an endocrine disorder in which the parathyroid glands in the neck do not produce enough parathyroid hormone (PTH). "Here, we show that PTH1R exists as a monomer in live cells under both basal and ligand-bound conditions, even in the presence of a dimeric form of the PTH mutant, PTHR25C (residue 25 of PTH), which is linked with hypoparathyroidism." (PMID 41203134, 2025). "Moreover, the dimeric form of the PTH mutant PTHR25C (encountered in idiopathic hypoparathyroidism), which restores the structural and signaling defects caused by the PTH mutation, also operates through a PTH1R monomer." (PMID 41203134, 2025).
Ollier disease (9 papers, 2006 to 2024). A rare primary bone dysplasia disorder characterized by the development of multiple mainly unilateral or asymmetrically distributed enchondromas throughout the metaphyses of the long bones. "A further disease associated with PTH1R gene disorder is Ollier disease (OMIM #166000), an enchondromatosis with an asymmetric dwarfism and epiphyseal fusion abnormality." (PMID 27898723, 2016). "Previously, PTH1R was reported to be the gene causing Ollier disease." (PMID 21235737, 2011). "Patients with enchondromatosis (Ollier disease and Maffucci syndrome, OMIM 166000) are endowed with inactivating mutations in the Parathyroid hormone 1 receptor (PTH1R), while mice with the PTH1R mutation at codon 150 develop multiple enchondroma-like lesions with upregulated Hh signaling." (PMID 31757091, 2019).
chondrodysplasia (8 papers, 2008 to 2025). "Severe loss-of-function homozygous mutations in PTH1R are incompatible with life as in Blomstrand’s lethal chondrodysplasia, characterized by accelerated growth plate ossification." (PMID 40904804, 2025). "Together, the prevalence of PFE and number of patients displaying genetic heterogeneity, and the compiled results of Blomstrand chondrodysplasia and PFE mutations indicate that PFE caused by mutations in PTH1R is potentially underestimated." (PMID 24058597, 2013).
osteoarthritis (8 papers, 2010 to 2025). A noninflammatory degenerative joint disease occurring chiefly in older persons, characterized by degeneration of the articular cartilage, hypertrophy of bone at the margins and changes in the synovial membrane. "PTH1R mutations were found in five PFE patients from two families who also had osteoarthritis." (PMID 38002872, 2023). "Mutations of Pth1r causing PFE have also been linked to osteoarthritis." (PMID 28239357, 2017). "In the pathophysiology of cartilage and osteoarthritis, PTH1R mediates anabolic responses to intermittent PTH administration, promoting bone formation and subchondral bone integrity." (PMID 40860192, 2025). "Collectively, PTH1R and CaSR represent opposing regulators in osteoarthritis: PTH1R exerts protective effects via bone-cartilage crosstalk, while CaSR drives pathological differentiation and matrix breakdown, highlighting their therapeutic potential as targets for osteoarthritis management." (PMID 40860192, 2025). "Furthermore, iPTH failed to decrease the number of COX2+ cells and the level of PGE2 in tibial subchondral bone in Pth1r−/− mice, indicating that iPTH modulated the level of PGE2 in subchondral bone in osteoarthritis through its effects on subchondral bone." (PMID 33646122, 2021). "In the Pth1r−/− mice after DMM surgery, PTH failed to improve osteoarthritis pain and reduce the sensory innervation and the level of PGE2 in the subchondral bone, but PTH worked effectively in Pth1r+/+ mice." (PMID 33646122, 2021).
primary failure of tooth eruption (6 papers, 2013 to 2023). "In contrast to this homozygous disease, we and others have described the incidence of heterozygous PTH1R mutations which may inactivate PTH1R function in Primary Failure of Tooth Eruption (PFE) (MIM #125350)." (PMID 27898723, 2016). "Primary failure of tooth eruption (PFE) is causally linked to heterozygous mutations of the parathyroid hormone receptor (PTH1R) gene." (PMID 27898723, 2016). "Primary Failure of tooth Eruption (PFE) is a non-syndromic disorder which can be caused by mutations in the parathyroid hormone receptor 1 gene (PTH1R)." (PMID 24058597, 2013). "The cause is generally attributed to resorption of the permanent periodontal membrane due to malfunction in the peripheral nerve tissue (genetically determined or caused by virus attacks) or primary failure of tooth eruption (PFE) (defect in the receptor for parathyroid hormone, PTH1R)." (PMID 36980140, 2023).
ankylosis (4 papers, 2018 to 2026). Fixation and immobility of a joint. "If a patient is believed to have PFE, a genetic test for a mutation in the PTH1R gene should be recommended before any orthodontic therapy so as to prevent ankylosis." (PMID 35740708, 2022). "If a patient is suspected of having PFE, a genetic test for mutation in the PTH1R gene should be recommended prior to any orthodontic treatment to avoid ankylosis." (PMID 29544499, 2018). "If PFE is suspected in a patient, a genetic test for mutation in the PTH1R gene should be recommended prior to any orthodontic treatment to avoid ankylosis." (PMID 29544499, 2018). "We found 20 patients with variants in PTH1R: 3 with PFE diagnosis, 12 with ankylosis, and 5 with MFE diagnosis." (PMID 40608218, 2025). "The remaining 19 cases, in which no variants of the PTH1R gene were found, were considered cases of ankylosis." (PMID 40608218, 2025). "The remaining 19 cases without variants of the PTH1R gene were considered cases of ankylosis." (PMID 40608218, 2025). "In PFE the tooth begins to erupt, while in ankylosis it remains closer to the basal bone: ankylosis prevents the tooth from erupting, while the tooth affected by PFE has an absent or reduced capacity to erupt depending on the incomplete penetrance of the PTH1R gene." (PMID 40608218, 2025).
hyperparathyroidism (4 papers, 2008 to 2023). Hyperfunction of the parathyroid glands resulting in the overproduction of parathyroid hormone. "Increased expression of Pth1r has been associated with muscle fatigue, cardiovascular pathology and hyperparathyroidism as well as skeletal muscle wasting." (PMID 34302016, 2021).
Hypocalcemia (4 papers, 2022 to 2025). An abnormally decreased calcium concentration in the blood. "Three PTH1R mutations found in patients with symptomatic hypocalcemia and PTH resistance map to the receptor TM1 (R186H) and TM2 (D241E and I237N)." (PMID 40904804, 2025). "Recently, two nonlethal homozygous PTH1R mutations were identified in two unrelated families in which affected members exhibit either dental and skeletal abnormalities (PTH1R‐V204E) or hypocalcemia and hyperphosphatemia (PTH1R‐R186H)." (PMID 35720667, 2022). "Furthermore, magnesium acts as a cofactor for adenylate cyclase, and its deficiency can disrupt signal transduction at the parathyroid hormone 1 receptor (PTH1R), contributing to hypocalcemia." (PMID 39897293, 2025). "Seven homozygous non-lethal PTH1R mutations were recently described in patients with various degrees of delayed ossification and PFTE, associated with PTH-resistant hypocalcemia in some cases." (PMID 40904804, 2025).
Jansen's metaphyseal chondrodysplasia (4 papers, 2021 to 2025). "Homozygous PTH1R mice show normal growth and skeletal structures, as well as normal mineral ion homeostasis, and therefore offered the opportunity to generate mice expressing the PTH1R with the H223R mutation, the most common cause of Jansen's disease, under proper spatiotemporal control." (PMID 37808400, 2023).
neuroblastoma (4 papers, 2019 to 2024). Neuroblastoma (NB) is the most common solid, extracranial childhood tumor. "Taken together, these results indicate that higher expression of PTH1R is associated with a more differentiated, less aggressive phenotype, and its downregulation increases neuroblastoma cell migration and invasion in vitro." (PMID 31293052, 2019). "Also, PTH1R knockdown is associated with a more aggressive phenotype, and increases cell migration, invasion, and anchorage‐independent growth in neuroblastoma." (PMID 31293052, 2019). "Accordingly, these morphological changes were associated with a decrease in neuroblastoma cell differentiation markers and upregulation of epithelial‐to‐mesenchymal transition and stem cell markers, thus suggesting a less differentiated stage upon PTH1R downregulation." (PMID 31293052, 2019). "We here investigate the role of PTHLH and PTH1R in neuroblastoma and show their contribution to neuroblastoma behavior, both benign and malignant." (PMID 31293052, 2019). "Consistent with the reported results, U2OS sh‐PTH1R derivatives showed decreased migratory and invasive capacities, in sharp contrast with phenotypes observed in neuroblastoma cell lines." (PMID 31293052, 2019). "The aim of this study was to functionally assess the role of PTHLH and its receptor, PTH1R, in neuroblastoma." (PMID 31293052, 2019). "We here show that PTHLH and its receptor PTH1R play a role in neuroblastoma cell migration and invasion." (PMID 31293052, 2019). "Stable knockdown of PTHLH and PTH1R was conducted in neuroblastoma cell lines to investigate the succeeding phenotype induced both in vitro and in vivo." (PMID 31293052, 2019). "All these data considered, the aim of this work was to functionally analyze the role of PTHLH and its receptor, PTH1R, in neuroblastoma." (PMID 31293052, 2019). "All these data together reinforce the idea of an oncogenic; intracrine role of PTHLH is acting in more aggressive neuroblastomas, whereas a PTH1R‐dependent, paracrine role of PTHLH would be predominant in good prognosis primary tumors." (PMID 31293052, 2019). "Furthermore, for the group of to the group of embryonal malignancies it was shown that neuroblastoma cell lines not only respond to PTH in culture but that PTHrP differentially regulates neuroblastoma cell via action on PTH1R." (PMID 39141058, 2024). "Recently, in neuroblastoma it has been reported that the oncogenic role of PTHrP is a consequence of its intracrine function, as downregulation of its receptor, PTH1R, increased anchorage independent growth and induced a more undifferentiated, invasive phenotype." (PMID 35761298, 2022). "Indeed, PTH1R knockdown increased cell migration and invasion and decreased tumor differentiation in neuroblastoma but had an opposite effect in osteoblastoma." (PMID 35203352, 2022). "Then, PTH1R expression levels were assessed in neuroblastoma cell lines." (PMID 31293052, 2019). "PTH1R mRNA was found significantly higher in patients with age at diagnosis < 18 months and in MYCN nonamplified neuroblastomas, although this was not an independent predictor of outcome in multivariate analyses." (PMID 31293052, 2019). "Contrarily, our data indicate that PTH1R expression is higher in the least malignant, MYCN nonamplified neuroblastic tumors, and its knockdown promoted increased cell invasion and migration in neuroblastoma cell lines." (PMID 31293052, 2019).
pseudohypoparathyroidism (4 papers, 2022 to 2025). "The data support a general decrease in PTH1R surface expression and/or function as a mechanism for PFE and a selective impairment in PTH ligand affinity as a potential PTH1R‐mutation‐based mechanism for pseudohypoparathyroidism." (PMID 35720667, 2022). "Even if both L388R and E392K mutations give rise to pseudohypoparathyroidism, successfully developing a potential ligand for restoring cAMP production upon PTH1R stimulation could be highly mutation-dependent." (PMID 40392940, 2025).
secondary hyperparathyroidism (4 papers, 2016 to 2025). Overproduction of parathyroid hormone in response to influence external to the parathyroid glands. "These include PHP, secondary hyperparathyroidism due to chronic vitamin D deficiency or renal dysfunction, and rare PTH receptor (PTH1R) mutations that can mimic PHP phenotypes." (PMID 41322012, 2025). "Interestingly, in patients with secondary hyperparathyroidism, there is an increased prevalence of LV-hypertrophy, which was reversed after parathyroidectomy and a subsequent reduction of PTH levels, strengthening the notion that the PTH-1R participates in the CAS and hypertrophic mechanism." (PMID 39941574, 2025).